IDH2 (isocitrate dehydrogenase (NADP(+)) 2)
Diseases named in the same sentence as IDH2 in open-access papers (continued):
Sharing a sentence is not in itself a finding about the gene and the disease.
glioma (continued). "Different cancers have mutations in IDH1 and IDH2, including a fraction of acute myeloid leukemia, low-grade glioma, secondary glioblastoma, chondrosarcoma, and cholangiocarcinoma." (PMID 35831624, 2022). "This represents an important finding that has the potential to refine the utility of WGMA to predict the IDH1/IDH2 mutation status of gliomas, thus improving diagnostic yield and efficiency of laboratory testing compared to single analyte IDH1/IDH2 tests." (PMID 36360312, 2022). "Various somatic point mutations of IDH1 or IDH2 have been discovered in a variety of malignancies in recent years, such as gliomas and AMLs (acute myeloid leukemias)." (PMID 36188571, 2022). "IDH1/IDH2 mutation is a common feature of gliomas and is associated with a glioma-CpG island methylator phenotype (CIMP)." (PMID 36360312, 2022). "Two hotspots for IDH1/IDH2 mutation have been described in gliomas: IDH1 codon 132 (p.R132) and IDH2 codon 172 (p.R172)." (PMID 36360312, 2022). "Specifically, IDH1 or IDH2 are usually mutated in WHO grade II/III glioma or secondary GBM patients, mainly in the frontal lobe (75%) and temporal lobe (40%)." (PMID 36556190, 2022). "In routine clinical diagnostic practice, the presence of positive immunohistochemical staining for IDH1 R132H within a glioma obviates the need to sequence IDH1 or IDH2, as the clinically relevant mutation has been identified." (PMID 36286062, 2022). "Molecular biomarkers, such as IDH1/IDH2 mutations and 1p19q co-deletion, are included in the histopathological and clinical criteria currently used to diagnose and classify gliomas." (PMID 36360312, 2022). "A mutant IDH2 gene (IDH2 R172K or R172M) has additionally been identified in glioma subsets, although less frequently than IDH1 mutations." (PMID 35804976, 2022). "While IDH2 mutations are common in haematological malignancies, they are relatively uncommon in gliomas, although they are also affected at an arginine residue." (PMID 36286062, 2022). "Mutation can occur in the genes coding for either IDH1 or IDH2 genes, but in over 90% of infiltrating gliomas with IDH mutation, the detected variant is IDH1 R132H." (PMID 36397144, 2022). "Both IDH1 (isocitrate dehydrogenase 1) and IDH2 (isocitrate dehydrogenase 2) mutations play a vital role in the development of gliomas through disruption of normal cellular metabolic processes." (PMID 36286062, 2022). "It is seen in approximately 80% of WHO grade II/III gliomas and in 4–12% of GBM, whereas only a minority of gliomas (4–8%) harbor an IDH2 mutation." (PMID 35158978, 2022). "IDH1 mutations at R132 have been associated with astrocytomas, GBM, and oligodendrogliomas, and IDH2 mutations at R172 have been linked with gliomas.IDH1/2 have been linked to enhanced reductive carboxylation in hypoxia for de novo lipogenesis." (PMID 36643416, 2022). "The maximum mutation’s frequency of IDH1 is more than 90% in gliomas, while the mutation’s frequency of IDH2 is less than 5%." (PMID 36091829, 2022). "Accurate detection of IDH1/IDH2 mutation and 1p19q co-deletion status is important for appropriate tumor classification of gliomas under the most recent 2021 WHO classification of central nervous tumors." (PMID 36360312, 2022). "Somatic IDH1/IDH2 mutations occur in approximately 80% of gliomas and secondary glioblastomas but in less than 10% of primary glioblastomas." (PMID 36360312, 2022). "Other studies of IDH1 and IDH2 mutations in gliomas point to them as having distinct mutational and clinical patterns." (PMID 36042521, 2022). "A subset of these gliomas contains mutations in isocitrate dehydrogenase 1 (IDH1mut) or, less commonly, IDH2 (together called “IDHmut”)." (PMID 35134075, 2022). "Considering that IDH co-occurring mutations in different IDH1 loci or in IDH1 and IDH2 loci are extremely rare events in gliomas, our finding is of special interest to the field." (PMID 35740557, 2022).
glioma (continued). "IDH2 mutations are frequently found in glioma, chondrosarcoma, and acute myeloid leukemia and mainly occur in the active-site arginine residues of R140/R1728–11." (PMID 36335201, 2022). "Interrogation of cancer genomic databases and a systematic review was undertaken, demonstrating the rarity of the co-occurrence of IDH1 and IDH2 mutations in a variety of cancer types, and in glioma specifically." (PMID 36286062, 2022). "Point mutations in both IDH1 and IDH2 have been frequently associated in the pathogenesis of a subset of gliomas, mainly low-grade gliomas and secondary glioblastomas." (PMID 34884868, 2021). "In 2016, the revision of the WHO classification of CNS tumors has highlighted the importance of the IDH1 or IDH2 mutation and co-deletion of chromosomal arms 1p and 19q for the diagnosis of gliomas." (PMID 33493139, 2021). "The detection of 2HG by MRS can aid in the diagnosis of rare, non-IDH1-R132H IDH1 and IDH2 mutations in gliomas." (PMID 34829476, 2021). "A number of IDH1 and IDH2 mutations have been reported in glioma, with the most common a base substitution in codon 132 of IDH1 resulting in an arginine to histidine replacement (IDH1R132H)." (PMID 33842321, 2021). "It has been shown that patients with IDH1 and IDH2 mutated gliomas have better survival rates than patients with IDH wild type tumors." (PMID 34557149, 2021). "Our analysis of cancer data from The Cancer Genome Atlas revealed a high incidence of IDH1 and IDH2 mutations in subtypes of gliomas." (PMID 35996504, 2021). "In conclusion, we identified a high incidence of IDH1 and IDH2 mutations in a tissue-specific manner most notably in gliomas, and various types of skin cancer suggesting a potential role in the pathogenesis of these solid malignancies." (PMID 35996504, 2021). "Previous series strongly suggest that patients with IDH2 mutated glioma more frequently host a 1p19q codeletion than those with IDH1 alterations." (PMID 33669525, 2021). "The discovery of IDH1 and IDH2 mutations led to a biomarker defined classification of gliomas based on prognosis and treatment response." (PMID 34597473, 2021). "The present study is limited by the relatively small number of patients in the subgroup analyses, especially in the case of gliomas with 1p/19q codeletion and IDH2 mutation." (PMID 34912706, 2021). "IDH2 mutation contribute a small population of gliomas, which cannot be identified by PET analysis now." (PMID 33472598, 2021). "Either IDH1 or IDH2 mutations are a defining classification for adult gliomas, with vast majority of gliomas as IDH1 mutations." (PMID 33599882, 2021). "In Non-Redundant, the frequency of IDH1 mutation was 100% in lower-grade glioma, and cancer types with IDH2 mutation >10% included acute myeloid leukemia, myelodysplastic syndromes, and primary central nervous system lymphoma." (PMID 34440884, 2021). "Subsequent study identified that IDH1/IDH2 mutations were more prevalent in WHO grade II/III glioma than GBM, and patients occurred IDH gene mutations share a better outcome than those of wildtype IDH genes." (PMID 34121368, 2021). "Recently, the World Health Organization (WHO) added the presence of one of the recurrent point mutations in the isocitrate dehydrogenase genes (IDH1 or IDH2) and co-deletion of chromosomal arms 1p/19q to the glioma diagnosis criteria." (PMID 33926464, 2021). "These advances collectively demonstrate that the IDH1 and IDH2 mutations play a key role in the therapeutic determination of gliomas and a subset of other malignancies." (PMID 35996504, 2021).
glioma (continued). "Mutations in the NADPH-linked mitochondrial isoforms of IDH1 and IDH2 have led to impaired energy production in the mitochondria and thus, provide clear evidence for mitochondrial dysfunction in gliomas." (PMID 33802571, 2021). "Mutations in the IDH1 and IDH2 genes are well described in lower-grade gliomas (grade II and III astrocytomas and oligodendrogliomas) and secondary glioblastomas, where they have an incidence of more than 70 %." (PMID 34641967, 2021). "Of particular note, the significance of 1p/19q codeletion and mutation of isocitrate dehydrogenase 1 or 2 (IDH1-mt or IDH2-mt) has recently been established with regard to the prediction of the prognosis of gliomas." (PMID 34513462, 2021). "Isocitrate Dehydrogenase 1/2 (IDH1 and IDH2) mutations (IDHmut) are the most common genetic alteration in glioma grade II and III and secondary glioblastoma and these mutations increase reliance on glutamine metabolism, suggesting a potential vulnerability." (PMID 33681764, 2021). "In MSK_Impact, IDH1 alteration was 33% in various types of gliomas and 14% in hepatobiliary cancer, whereas IDH2 mutation was seen most frequently in mature T and NK neoplasms." (PMID 34440884, 2021). "Mutations in IDH1 and IDH2 genes are present in a majority of the low-grade gliomas and define a subtype associated with favorable prognosis." (PMID 33272320, 2020). "Since glial tumors have a truly diffusely infiltrating growth pattern within the brain, to date only IDH1/IDH2-mutated glioma cells can be sharply distinguished form reactive glia, using immunostaining." (PMID 32240464, 2020). "Apart from various genetic events, the discovery of IDH1 and IDH2 mutations has recently been the most exciting recent discovery in understanding oncogenetic events of glioma." (PMID 33552543, 2020). "The amino acid substitution from Arg172 to lysine (K) is the most common variant present in IDH2-mutated glioma." (PMID 32825279, 2020). "The IDH2 inhibitor AG-221 is being studied in patients with advanced solid tumors or gliomas or R/R AITL who harbor these mutations (NCT02273739)." (PMID 32448357, 2020). "Isocitrate Dehydrogenase mutations, IDH1, and IDH2 have been found in gliomas, and classifying gliomas based on their molecular profiling of IDH status (mutated vs. wild-type) creates clinically distinct groups." (PMID 32111869, 2020). "Findings of our methods are validated by finding that for LGG, IDH1 and IDH2 mutations are selected, given the well-known prognostic value of mutations in these genes for predicting glioma survival." (PMID 33081688, 2020). "In this study, we explored IDH1, IDH2, and TERTp mutation status in a cohort of patients with gliomas from the WHO grade II to IV to identify the frequencies of these mutations in Chinese patients with gliomas." (PMID 32146731, 2020). "On the other hand, IDH2 mutations occurred less frequently in gliomas and were mutually exclusive of IDH1 mutations." (PMID 31963897, 2020). "The Hallmark bile acid metabolism pathway includes IDH1 and IDH2, which also have known glioma associations." (PMID 33081688, 2020). "The major mutation in glioma is IDH1/IDH2, which is a key metabolic gene in the oxidative decarboxylation of isocitrate in tricarboxylic acid (TCA) cycle, converting isocitrate to ɑ-ketoglutarate as reducing NADP+ to NADPH26." (PMID 31897239, 2020). "IDH2 mutations rarely occur in gliomas and are commonly limited to IDH1 mutations (Dunn, Andronesi, & Cahill, 2013)." (PMID 32146731, 2020). "For example, adult low-grade astrocytomas and the higher grade gliomas which arise from malignant progression often possess IDH1 or IDH2 gene mutations." (PMID 32375301, 2020). "In 2008, compelling research showed that mutations in isocitrate dehydrogenase (IDH1 and IDH2) are frequently identified in the World Health Organization (WHO) grade II/III gliomas and secondary glioblastomas (GBMs)." (PMID 32825279, 2020).
glioma (continued). "In 2016 WHO classification, codeletion of chromosomal arms 1p/19q (1p/19q codeletion) and isocitrate dehydrogenase 1 or 2 (IDH1 or IDH2) were included in diagnostic typing for glioma classification." (PMID 33330074, 2020). "DNA sequence evaluation of the IDH2 exon in glioma samples revealed that all the nine somatic mutations were at residue R172: The R172 residue in IDH2 is the exact analog of the R132 residue in IDH1." (PMID 33552543, 2020). "We do realize though, that levels of 2HG produced by IDH2 WT in this work are by two orders of magnitude lower than in glioma malignancies harbouring IDH2 oncogenic heterozygous mutations." (PMID 32457458, 2020). "With respect to the field “epigenetics,” the discovery of mutation to the IDH1 and IDH2 genes in gliomas has determined the prosperity of subsequent glioma and epigenetic studies." (PMID 30717468, 2019). "Among the three IDH enzymes, IDH1 and IDH2 are frequently mutated in glioma and hematological malignancies." (PMID 31695915, 2019). "Mutations in IDH1 and IDH2 are seen in over 80% of lower-grade gliomas (WHO grades II and III) and secondary GBMs that are thought to later develop from lower-grade lesions." (PMID 31165048, 2019). "According to WHO 2016 update, diffusely infiltrating oligodendroglioma is a slow-growing glioma with IDH1 or IDH2 mutation and codeletion of chromosomal arms 1p and 19q (1p19q-codeletion)." (PMID 31853670, 2019). "Recently, the inhibitor entered clinical trials for the treatment of patients with advanced solid tumors including glioma, chondrosarcoma, and cholangiocarcinoma with a mutated IDH2." (PMID 30857299, 2019). "miR-183 has been shown to suppress IDH2, which causes a decrease of α-KG levels and a subsequent increase in aerobic glycolysis in glioma cells." (PMID 31817761, 2019). "The frequency of IDH2 R172K mutations in IDH-mutated glioma is 1.4%, followed by R172M (0.6%) and R172W (0.2%)." (PMID 30791611, 2019). "Recently, increasing evidence has suggested recurrent point mutations in isocitrate dehydrogenase genes (IDH1 and IDH2) occur in specific types of glioma." (PMID 31681612, 2019). "IDH1 and IDH2 are mutated in over 75% of low grade gliomas and secondary glioblastoma multiforme (GBM)." (PMID 31311166, 2019). "Further studies have found that the IDH1 R132H mutation is the most common mutation in gliomas, while the IDH2 gene also undergoes similar mutations at R172, but the frequency of such mutations are relatively low." (PMID 31263678, 2019). "This proposal is supported by a recent study demonstrating enriched gene sets related to oxidative phosphorylation in the IDH2 mutation subset of glioma patients." (PMID 30791611, 2019). "Over 90% of the reported IDH mutations in glioma patients affects the IDH1 gene at codon R132H, whereas mutations in the IDH2 gene are less common, affecting 2.4% of gliomas." (PMID 30791611, 2019). "It has been reported that mutations of IDH1 and IDH2 occur in the vast majority of low-grade gliomas and secondary high-grade gliomas, and also in some cases of AML." (PMID 30984620, 2019). "Instead, gain-of-function mutations of IDH1 and IDH2 isoforms lead to the production and accumulation of L- and D-2-hydroxyglutarate (L-/D-2HG) in acute myeloid leukemia, glioma, chondrosarcoma, and cholangiocarcinoma." (PMID 31366176, 2019). "Subsequent studies identified mutations in either IDH1 or IDH2 in over 70% of lower-grade gliomas, as well as a small subset (~5%) of secondary glioblastomas that evolved from lower-grade precursors." (PMID 31788444, 2019). "First of all, in accord with in vitro studies, the mitochondrial IDH2 mutations manifested a significantly elevated 2-HG/tCho metabolite ratio compared to gliomas with the cytosolic IDH1 mutation." (PMID 30791611, 2019).
glioma (continued). "When IDH1 or IDH2 is mutated in gliomas (most frequently at codon R132 or R172, respectively), the mutated protein gains a neomorphic enzymatic activity, and produces D-2-hydroxyglutarate (2-HG) from α-ketoglutarate (α-KG)." (PMID 31652645, 2019). "Another recent prominent example of metabolism-associated genes being discovered for functional implication in malignant transformations is the mutation of the isocitrate dehydrogenase 1 and 2 (IDH1/IDH2) in gliomas and acute myeloid leukemia." (PMID 31454887, 2019). "IDH1 p.Arg132His is the predominant IDH pathogenic variant in glioma (90%) and IDH2 p.Arg140Trp is one of the hotspot variants commonly seen in acute myeloid leukemia and only rarely observed in gliomas." (PMID 31604779, 2019). "ATRX deficiency almost invariably co-occurs with mutations in IDH1 or its homologue IDH2 in adult gliomas." (PMID 30808951, 2019). "Currently, IDH1 and IDH2 mutations have been identified in acute myelogenous leukemia, low-grade glioma, and secondary glioblastoma." (PMID 31263678, 2019). "Since the initial discovery of IDH mutations in cancer in 2008, recurrent somatic mutations in IDH1 and IDH2 have been identified in different malignancies, including gliomas, thyroid carcinomas, cholangiocarcinomas, sarcomas, and AML." (PMID 31695915, 2019). "Point mutations in IDH1 and IDH2 are detected in different types of malignancies such as glioma and glioblastoma, acute myeloid leukemia (AML), and head and neck squamous cell carcinoma (HNSCC)." (PMID 30744183, 2019). "Both mutated IDH1 and IDH2 are common in adult gliomas (WHO grades II and III) and secondary GBM (WHO grade IV)." (PMID 30625996, 2019). "Mutations in IDH1 and IDH2 have been known to be a key development of many gliomas with information regarding outcomes and response to therapy." (PMID 30046944, 2018). "Glioma patients with IDH1 or IDH2 mutation have a significantly better prognosis than patients with wild-type IDH." (PMID 29914429, 2018). "The IDH1 and IDH2 mutations were subsequently indentified in the majority of lower grade gliomas, mostly in diffuse astrocytomas (62%), anaplastic astrocytomas (46%), oligodendrogliomas (77%), and anaplastic oligodendrogliomas (73%)." (PMID 29662659, 2018). "In IDH1 (the cytosolic NADP-dependent isoform), almost all gliomas are associated with an active site R132H mutation, whereas in IDH2 (the mitochondrial NAD-dependent homolog), the main active site mutation is R172K." (PMID 29772792, 2018). "As a result, the WHO classification for central nervous system tumors was recently modified to include mutations in IDH1/IDH2 as a critical part of the diagnosis of infiltrating gliomas." (PMID 30170631, 2018). "Mutations of both isocitrate dehydrogenase isoforms (IDH1 and IDH2) are linked to tumorigenesis and are detected in acute myeloid leukaemia, colorectal cancers, and in a large proportion of high grade gliomas and glioblastomas." (PMID 29772792, 2018). "The heterozygous R132H mutation in IDH1 accounts for 95% of IDH1/2 mutations in gliomas, however heterozygous mutations also occur in the analogous amino acid of IDH2 (R172), including R172G, R172K, and R172M." (PMID 30647847, 2018). "Glioma survival is strongly associated with the IDH1/IDH2 mutation, with IDH1 wild-type typically being associated with poorer outcomes." (PMID 29099032, 2017). "Mutations of isocitrate dehydrogenase 1 and 2 (IDH1 and IDH2) gene were recently discovered in vast majority of World Health Organization (WHO) grade II/III gliomas." (PMID 28052098, 2017). "Of the many molecular changes found in gliomas, mutations in IDH1 or IDH2 occur early during glioma formation, and are associated with better overall survival (OS)." (PMID 28851427, 2017). "The most common mutations identified to date are in the IDH1/IDH2 genes with IDH1 mutations identified in approximately 80% of grade 2/3 gliomas." (PMID 29099032, 2017).